FN1 (fibronectin 1)
Diseases named in the same sentence as FN1 in open-access papers (continued):
Sharing a sentence is not in itself a finding about the gene and the disease.
cataract (2 papers, 2018 to 2023). Partial or complete opacity of the crystalline lens of one or both eyes that decreases visual acuity and eventually results in blindness. "In this study, a miRNA-mRNA network was constructed which contains miR-206-3p, miR-493-5p, miR-493-3p, miR-193b-3p, miR-200a-3p, miR-29a-3p, miR-29b-3p, miR-29c-3p, Bfsp1, Plp1, Cnp, Nfasc, Mbp, Pygm, Bfsp2 and Fn1, whose dysregulation may be associated with the cataract pathogenesis." (PMID 37974089, 2023). "In the Na2SeO3-induced cataract group, the level of Fn1 was decreased, with a marked difference from the control group, indicating Fn1 participates in the process of cataract." (PMID 37974089, 2023). "Furthermore, the analysis of TGF-β-responsive genes by RT-qPCR showed increased expression of collagen (COL1A1), fibronectin (FN1), Snail, matrix metalloproteinase 2 (MMP2), and matrix metalloproteinase 9 (MMP9) in the cataracts of transgenic mice as compared to nontransgenic lens samples." (PMID 29888254, 2018).
cervical squamous cell carcinoma (2 papers, 2022 to 2025). A squamous cell carcinoma arising from the cervical epithelium. "Furthermore, compared to normal cervical tissues, the protein expression of FN1, ICAM1, and PLAU was significantly upregulated in cervical squamous cell carcinomas." (PMID 40141137, 2025).
colitis (2 papers, 2021 to 2025). Inflammation of the colon. "Moreover, a slight decrease of colon mRNA expression of extracellular matrix-associated genes Fn1, Col1a1, Col3a1 and Tgf-β was observed in colitis mice receiving SuperMApo treatment." (PMID 35003066, 2021).
coronary atherosclerosis (2 papers, 2024 to 2026). Atherosclerosis of the coronary vasculature. "In airway epithelium, FN1 was upregulated in anaphylactic sudden death (ASD) and anaphylactic sudden death (ASD) with Coronary Atherosclerosis (ASD + CAS) groups, while GP1BA was downregulated." (PMID 41828395, 2026). "Interestingly, PLG, ITIH4, FN1, and ANGPTL4, all protective against MI, were also inferred to be protective against coronary atherosclerosis." (PMID 40027362, 2024).
dengue virus infection (2 papers, 2019 to 2021). "The FCPLJ treatment downregulated ITGB3, ICAM1 and FN1 genes, which were upregulated during dengue virus infection." (PMID 30944031, 2019). "The FCPLJ treatment has affected the regulation of four genes, CCL-2/MCP-1 (upregulated), ITGB3, ICAM1 and FN1 (downregulated), which were involved in endothelial permeability regulation during dengue virus infections." (PMID 30944031, 2019). "The FCPLJ treatment upregulated monocyte chemoattractant protein 1 and downregulated intercellular adhesion molecule 1, integrin beta 3 and fibronectin 1 genes during dengue virus infection." (PMID 30944031, 2019). "Furthermore, the FCPLJ treatment has also downregulated the genes associated with the endothelial cell biology (ITGB3, ICAM1 and FN1) that are involved in the endothelial permeability process during dengue virus infection." (PMID 33919457, 2021).
Duchenne muscular dystrophy (2 papers, 2020 to 2024). Duchenne muscular dystrophy (DMD) is a neuromuscular disease characterized by rapidly progressive muscle weakness and wasting due to degeneration of skeletal, smooth and cardiac muscle. "COL1A2, FBN1 and FN1 may be novel biomarkers for DMD, and the siRNAs designed in our study were help to develop adjunctive therapy for Duchenne muscular dystrophy." (PMID 38762732, 2024). "Fibronectin was described as a seric biomarker of Duchenne muscular dystrophy (DMD), and its expression during fibrosis has been shown to be regulated by TGFB1 and CTGF, whose expression patterns follow those of FN1 in our study." (PMID 32670085, 2020).
focal segmental glomerulosclerosis (2 papers, 2022). A renal disorder characterized by sclerotic lesions in the glomeruli. "It was found that fibronectin 1 (FN1), epidermal growth factor (EGF), and transthyretin (TTR) showed considerable diagnostic efficiency for focal segmental glomerulosclerosis, which was based on bioinformatics analysis." (PMID 36199375, 2022).
gallbladder cancer (2 papers, 2017 to 2025). "According to the result of Cellchat, compared with low expression of ASPH, high expression of ASPH significantly enhances the FN1 signaling pathway and COLLAGEN signaling pathway between epithelial and fibroblast in the tumor microenvironment of gallbladder cancer." (PMID 40110547, 2025). "Accordingly, high expression of ASPH can activate the four pathways of FN1 signaling pathway, COLLAGEN signaling pathway, VISFATIN signaling pathway and SPP1 signaling pathway, these pathways occur mainly in the epithelial, myeloid cell, myeloid cell and macrophage of gallbladder carcinoma." (PMID 40110547, 2025).
human papillomavirus infection (2 papers, 2020 to 2024). "The upregulated genes (n = 135) included ATM, COL1A1, FN1, ITGA6, and LAMB1, which were found to be enriched in pathways related to human papillomavirus infection and herpes simplex virus 1 infection." (PMID 40226717, 2024).
invasive carcinoma (2 papers, 2024). A carcinoma that is not confined to the epithelium, and has spread to the surrounding stroma. "Other differentially expressed transcripts include S100A7, LCN2, CXCL14, and CD207 (decreasing expression from premalignant lesions to invasive carcinoma), as well as IDO1, IL6, IL8, THBS1, and FN1 (increasing expression from premalignant lesions to invasive carcinoma)." (PMID 38706595, 2024).
ischemic cardiomyopathy (2 papers, 2022 to 2025). Ischemic cardiomyopathy is a cardiomyopathy in which a weakness in the muscle of the heart due to inadequate oxygen delivery to the myocardium with coronary artery disease being the most common cause. "Based on the bioinformatics analysis, Myh6, Myh7, and Fn1 were selected to have pivotal roles in cardiac cell contraction and ischemic cardiomyopathy." (PMID 40271502, 2025).
keratoconus (2 papers, 2022 to 2025). A degenerative, structural disorder of the eye, characterized by a cone-shaped protrusion of the cornea. "And some of their target genes, such as FN1, COL12A1, TIMP3 and FBLN5, were associated with ECM and also down-regulated in keratoconus." (PMID 35821117, 2022).
kidney cancer (2 papers, 2022). Primary or metastatic malignant neoplasm involving the kidney. "Additionally, FN1 positive macrophages are associated with poor prognosis in kidney cancer patients, and Fn1 was detected among our 26 commonly upregulated genes." (PMID 36470862, 2022). "In kidney cancer, SLC7A11-positive macrophages were mainly detected in GPNMB positive or FN1 positive macrophage sub-clusters." (PMID 36470862, 2022). "FN1+ TAM highly expressed fibronectin 1 (FN1) and scavenger receptor MARCO, which has been previously reported as a specific macrophage subset in kidney cancer." (PMID 36423636, 2022).
laryngeal carcinoma (2 papers, 2015 to 2021). Carcinoma that arises from the laryngeal epithelium. "Combining this information and the overexpression of FN1 in our study, it is assumed that FN1 plays a role in the development of laryngeal cancer." (PMID 25874882, 2015). "It noted up-regulation of S100A2, FGB, KRT17, FN1 and POSTN in laryngeal carcinoma tissues, as compared with normal tissue." (PMID 25874882, 2015). "Fibronectin 1 (FN1), which was found up-regulated in laryngeal cancer tissues in our study, is a glycoprotein that is involved in cellular adhesion and migration processes including wound healing, blood coagulation, host defense, and metastasis." (PMID 25874882, 2015).
liver cirrhosis (2 papers, 2022 to 2025). "The focal adhesion pathway encompasses several genes, and KEGG analysis demonstrated that AKT1, CTNNB1, EGFR, FN1, JUN, and SRC were strongly related to curcumin compounds that might be influenced by liver cirrhosis in our study." (PMID 36297027, 2022).
lymphedema (2 papers, 2017 to 2022). Excess fluid collection in tissues, causing swelling. "However, the overall analysis showed that lymphedema increases the mRNA expression of type I and type III collagen, connective tissue growth factor (CTGF), ACTA‐2, FN‐1 and MMP‐9." (PMID 35652284, 2022).
osteomalacia (2 papers, 2022 to 2025). Disorder caused by an interruption of the mineralization of organic bone matrix leading to bone softening, bone pain, and weakness. "PMTs are rare FN1-fusion-associated neoplasms of uncertain histogenesis and typically induce osteomalacia and hypophosphatemia due to FGFR1 induced secretion of Fibroblast growth factor 23 (FGF23)." (PMID 39404883, 2025).
Peri-Implantitis (2 papers, 2021 to 2025). An inflammatory process with loss of supporting bone in the tissues surrounding functioning DENTAL IMPLANTS. "The mRNA expression of FN1 in the peri-implantitis group was significantly higher than that in the control group." (PMID 34931168, 2021). "Finally, the potential target genes, namely, IL-6, TLR4, FN1, IL-1β, CXCL8, MMP-9, and SPP1, were found to be associated with peri-implantitis, and our results were consistent with those of previous studies." (PMID 34931168, 2021). "The intersecting genes, including IL6, TLR4, FN1, IL1β, CXCL8, MMP9, and SPP1, were revealed as potential genetic biomarkers and target genes of peri-implantitis." (PMID 34931168, 2021). "We found that IL-6, TLR4, FN1, IL-1β, CXCL8, MMP-9, and SPP1 might be used as potential biomarkers for the diagnosis of peri-implantitis." (PMID 34931168, 2021). "This study provides supportive evidence that IL6, TLR4, FN1, IL1β, CXCL8, MMP9, and SPP1 might be used as potential target biomarkers for peri-implantitis which may provide further therapeutic potentials for peri-implantitis." (PMID 34931168, 2021).
sarcoidosis (2 papers, 2016 to 2025). Sarcoidosis is a multisystemic disorder of unknown cause characterized by the formation of immune granulomas in involved organs. "Corresponding classification analysis of the two clinical subtypes of sarcoidosis revealed AUC values of 0.5 for FN1 and 0.6 for CCL2, illustrating the similarity in protein levels between the two subtypes of disease." (PMID 27259755, 2016). "Similar to NL and NXG, sarcoidosis lesional macrophages upregulated expression of the macrophage polarization marker genes MARCO, FCGR3A, NR1H3; the ECM-encoding gene FN1; the protease-encoding gene CTSS; and genes associated with inflammation, S100A8 and CHI3L1." (PMID 39989459, 2025). "However, in the final analysis we focused on Fibronectin 1 (FN1) and Chemokine (C-C motif) ligand 2 (CCL2) that had the strongest associations to sarcoidosis in both sample sets." (PMID 27259755, 2016). "While sarcoidosis fibroblasts also upregulated CXCL9 and CD74, they exhibited only modest increases in CCL5 and FN1." (PMID 39989459, 2025). "The two proteins with highest significance were fibronectin 1 (FN1, HPA027066) and C-C motif chemokine 2 (CCL2, HPA019163) with higher levels in the sarcoidosis group compared to the healthy controls (p < 0.001 in both sample sets)." (PMID 27259755, 2016). "Although the BAL fluid levels of both FN1 and CCL2 were increased in sarcoidosis patients compared to both healthy and diseased controls, the levels of these two proteins were more similar between the two subtypes of disease, i.e., in LS and non-LS patients." (PMID 27259755, 2016). "ROC analysis was applied to the data to evaluate how well the levels of FN1 and CCL2 could classify sarcoidosis patients from controls." (PMID 27259755, 2016). "Furthermore, our results showing no FN1 differences in serum of sarcoidosis patients compared to healthy controls mirror previous results in plasma." (PMID 27259755, 2016).
varicocele (2 papers, 2015 to 2020). A condition characterized by the dilated tortuous veins of the spermatic cord with a marked left-sided predominance. "Proteins associated with oxidative stress (PRDX2), DNA fragmentation (fatty acid synthase; FASN) and the inflammatory response (FN1) were also overexpressed in the bilateral varicocele group, indicating an increased inflammation and oxidative stress in this group, compared to unilateral varicocele." (PMID 32987677, 2020). "Some of the more abundant proteins in the unilateral varicocele group were lactotransferrin isoform 1 precursor (LTF), fibronectin isoform 3 preprotein (FN1), semenogelin-2 precursor (SEMG2), A-kinase anchor protein 4 isoform 2 (AKAP4), and semenogelin-1 preprotein (SEMG1)." (PMID 25890347, 2015).
Acanthamoeba infection (1 paper, 2019). "In our study, 3 patients with CNV following Acanthamoeba infection were analyzed and we surprisingly found that they showed the highest concentration of FN1 and TNC (+116%, p = 0.044 + 49.5% p = 0.012 compared to non-Acanthamoeba CNV patients)." (PMID 31582785, 2019).
Acanthamoeba keratitis (1 paper, 2019). Keratitis due to infection by acanthamoeba; it is usually associated with soft contact lens wear, particularly overnight wear. "Interestingly, among CNV patients, those affected with Acanthamoeba keratitis showed the highest levels of fibronectin-1 and tenascin-C, suggesting a specific role of these two proteins in Acanthamoeba driven corneal CNV." (PMID 31582785, 2019).
acne (1 paper, 2024). An inflammatory process of the sebaceous glands which is characterized by comedones, nodules, papules and/or pustules on the skin. "By modulating key structural genes like ELN, FN1, EGFR, and TIMP3, F3TAC supports ECM remodeling and wound healing, essential for addressing inflammation and tissue repair in acne-prone skin." (PMID 39684852, 2024).
adhesive capsulitis (1 paper, 2016). "In this study, we found higher levels of TNC and FN1 expression in glenohumeral synovium/capsule samples collected from patients with adhesive capsulitis compared to those collected from controls." (PMID 27438566, 2016). "Although only a slight increase in FN1 expression was detected in the glenohumeral capsules of the patients with adhesive capsulitis in the current study, our results suggest that FN1 may play a role in the fibrotic process." (PMID 27438566, 2016). "As such, TNC, FN1 and TGFβ1 receptor I may also play roles in adhesive capsulitis by contributing to capsule inflammation and fibrosis." (PMID 27438566, 2016). "The synovium/capsule samples from the patients with adhesive capsulitis had significantly higher TNC and FN1 expression than those from the controls." (PMID 27438566, 2016). "In the present study, we quantified the mRNA expression of the TGFβ1, TGFβR1, LOX, PLOD1, PLOD2, COMP, FN1, TNC and TNXB genes in glenohumeral synovium/capsule samples collected from patients with adhesive capsulitis and from controls." (PMID 27438566, 2016). "The patients with adhesive capsulitis had higher levels of TNC (p=0.005) and FN1 (p=0.043) expression compared to the controls." (PMID 27438566, 2016).
age (1 paper, 2024). A temporal measurement of the time period elapsed since an identifiable point in the life cycle of an organism. "TIMP3 upregulation preserves ECM integrity, crucial for skin resilience and regeneration, while FN1 and ELN actions further enhance wound healing and elasticity, mitigating age-related skin degradation." (PMID 39684852, 2024).
aortic valve calcification (1 paper, 2022). "Among DEGs not related to humoral immunity many overlap with those already implicated in aortic valve calcification, these include TNC, PRG4, COL11A1, SMOC2, FN1, and OGN." (PMID 36437309, 2022).
aortic valve disease (1 paper, 2022). "In this study, we believe that by stimulating the WNT/β-catenin signaling pathway, FN1 may play a critical role in the development of osteogenesis in calcified aortic valve disease." (PMID 35295271, 2022). "Thus, our findings suggest that the FN1 may be critical in the evolution of the inflammatory process in calcified aortic valve disease." (PMID 35295271, 2022).
Arterial thrombosis (1 paper, 2020). The formation of a blood clot inside an artery. "Platelet-derived Factor V (F5) was found to be a critical mediator of arterial thrombosis in mice and CAD patients show significantly higher levels of plasma FN1 as compared to healthy subjects, with platelet FN1 levels correlating with severity of disease." (PMID 32671099, 2020).
asthenozoospermia (1 paper, 2023). "In detail, the combination of the three proteins APCS, APOE, and FLOT1 predicts male subfertility in general, the two combined proteins APOE and FN1 predicts asthenozoospermia, and the two combined proteins RUVBL1 and TFKC oligoasthenozoospermia." (PMID 37048090, 2023). "Our results showed that sperm-derived Fibronectin 1 (FN1) was negatively correlated with sperm motility and showed a higher abundance level in men with asthenozoospermia." (PMID 37048090, 2023).
autism spectrum disorder (1 paper, 2025). A spectrum of developmental disorders that includes autism, and Asperger syndrome. "In this study, through the analysis of CHD8A and CHD8B allelic deletion samples, we identified seven hub genes associated with Autism Spectrum Disorder (ASD): IGF2, FN1, CXCR4, COL11A1, ITGA6, LOX, and FBN2." (PMID 40526590, 2025).
autoimmune disease (1 paper, 2022). A disorder resulting from loss of function or tissue destruction of an organ or multiple organs, arising from humoral or cellular immune responses of the individual to their own tissue constituents. "Based on the diverse systems biology and functional annotations of the 7 query genes, ITGAV, FN1, and HLA-DQB1 were prominent in autoimmune diseases." (PMID 35692981, 2022).
bone metastasis (1 paper, 2023). Transfer of a neoplasm from its primary site to bones. "Consistently, in the SU2C dataset, the higher FN1 expression with a median threshold was significantly associated with therapy resistance as measured by time on treatment in all 56 patients with different metastasis combined, which was even more significant in patients with bone metastasis." (PMID 36749798, 2023).
brain injury (1 paper, 2025). Acute and chronic (see also brain INJURIES, CHRONIC) injuries to the brain, including the cerebral hemispheres, CEREBELLUM, and brain STEM. "This interaction suggests that miR-200c may play a significant role in modulating the recovery and repair mechanisms following brain injury by influencing FN1 expression levels." (PMID 39129166, 2025).
cardiac interstitial fibrosis (1 paper, 2023). "After SAHA treatment, α-SMA intensity was reduced, as were cardiac interstitial fibrosis, and mRNA level of FN1 and LOX when compared with β2a-HFD-LN mice." (PMID 36763506, 2023).
cartilaginous tumors (1 paper, 2019). "FN1 gene fusions have been reported in PMTs, cartilaginous tumors, and more recently in calcifying aponeurotic fibromas." (PMID 31906059, 2019).
cholangiocarcinoma (1 paper, 2023). A carcinoma that arises from the intrahepatic biliary tree (intrahepatic cholangiocarcinoma) or from the junction, or adjacent to the junction, of the right and left hepatic ducts (hilar cholangiocarcinoma). "We performed survival analysis on TCGA cholangiocarcinoma (CHOL) patients based on FN1 and CD99 expression." (PMID 38239853, 2023).